ATF2 (activating transcription factor 2)
Diseases named in the same sentence as ATF2 in open-access papers (continued):
Sharing a sentence is not in itself a finding about the gene and the disease.
infection (33 papers, 2008 to 2025). The state of being infected such as from the introduction of a foreign agent such as serum, vaccine, antigenic substance or organism. "The ATF2 reporter was significantly activated by infection of plasmids expressing wtDVL1 and the DVL11529ΔG and DVL11615ΔA variants compared to infection of parent plasmid controls." (PMID 36916233, 2023). "Euclidean distance of samples showed highest similarity between replicates from each infection condition, with AP-1 and ATF-2 networks separating 5448-infected TEpi cells from mock-treated or JRS4-infected cells." (PMID 29868516, 2018). "Following infection the amount of phospho-ATF-2 was elevated at 4 hpi and continued to increase through 6 hpi (lanes 2–4)." (PMID 26437794, 2015). "It was reported in 2005 that infection of macrophages by Theiler's murine encephalomyelitis virus induces a type of demyelination in mice that that that resembles human MS, and also observed induction of ATF2 30 minutes after the infection of macrophages." (PMID 21152067, 2010). "The results indicate that HAdV-19 infection increased the phosphorylation of HSP27 (5-fold) and ATF-2 (6.5-fold) over mock infection." (PMID 18221537, 2008). "Shortly after infection, the enhanceosome consisting of NF-kB, IRFs, ATF2/cJun and the architectural protein HGMI(Y) is assembled at the Virus Responsive Element (VRE) region." (PMID 18225953, 2008). "HAdV-19 infection induced an increase in the ability of p38 MAPK to phosphorylate exogenous ATF-2 substrate at both 15 and 30 min post-infection as compared with p38 MAPK from mock infected cells." (PMID 18221537, 2008). "Furthermore, M. viscosa suppressed the expression of activating transcription factor 2 (atf2) at the lesion infection site, compared with all other groups." (PMID 35301338, 2022). "However, pretreated AGS cells using JB3-100 with mucin did not suppress VacA delivery into the AGS cells, and the levels of p-p38, p-ATF2 and Cox-2 proteins were therefore maintained compared with those in the infection group." (PMID 35095872, 2021). "Furthermore, we found that NK cells analyzed ex vivo during the acute phase of infection had significantly elevated levels of phosphorylated ATF2 and FOXO3A." (PMID 31467285, 2019). "infection in Atf2 mutant midguts, or in midguts depleted for Atf2 in ECs." (PMID 31554796, 2019). "Additionally, TAK1 depletion suppressed phosphorylation of JNK1/JNK2, p38 and one of their downstream targets, the transcription factor ATF-2, within 15–60 min of infection." (PMID 29581850, 2018). "Although the transcription factor NFIA was inhibited, ATF2 was activated by vvIBDV infection." (PMID 28086922, 2017). "In addition, we showed that Mekk1, Mkk3, p38c and Atf-2 function in a common pathway to control Duox transcription following infection." (PMID 25254641, 2014). "Infection of the human melanocyte line Hermes 3A with shATF2 effectively inhibited ATF2 expression, upregulated Mitf transcription and increased transcription of SOX10 and FOXD3 (from 7- to 10-fold) and to a lesser extent of Pax3 and Brn2 (from 1.5- to 2-fold)." (PMID 21203491, 2010). "How the nuoG mutant infection leads to an increase in TNF-α secretion by macrophages needs to be investigated in more detail but activation of transcription factors such as ATF-2, Elk-1 and c-Jun upon JNK activation have been reported and would lead to an increase in TNF-α gene transcription." (PMID 20421951, 2010). "GM-2 and GM-3 were predominantly associated with columnar epithelial responses and included regulators such as ATF2, CDX2, FOXJ2, and AHR, with infection-induced up-regulation of TFs such as SPI1, ESRRA, RFX1, and RARA." (PMID 41042872, 2025).
infection (continued). "During early-phase infection, there was robust upregulation of pro-inflammatory cytokines such as JUN, IL15, ATF2, TNFSF15, and CXCL10, indicating strong immune activation." (PMID 40649996, 2025). "For the cell host response in the early-phase infection, genes such as JUN, IL15, ATF2, TNFSF15, and CXCL10 were significantly upregulated, reflecting a strong pro-inflammatory and immune response." (PMID 40649996, 2025). "Here, we found that both colonic and ileal networks generated with CARNIVAL shared similar transcription factors, including ATF2/3, FOS, JUN, STAT1, and NFKB1, which were all upregulated in both tissues upon infection." (PMID 35501398, 2022). "Pathway enrichment tests identified a role for the AP-1, ATF-2, and NFAT transcription factor networks and GPCR signaling in TEpi cell responses to 5448 infection." (PMID 29868516, 2018). "Activation of p38 MAPK, that leads to activation of the transcription factor ATF-2 and the cyclic AMP response element-binding protein (CREB) was observed at 14 days post-infection but was then down-modulated at 28 days post-infection." (PMID 24967908, 2014). "We found that infection of corneal cells with HAdV-19 led to activation of p38 MAPK and its downstream targets, HSP-27 and ATF-2, within 15 to 30 minutes post-infection." (PMID 18221537, 2008). "Additionally, the virus appears to modulate transcription factors STAT3/STAT5, NELFE, ATF2, TAF7, and others, enhancing cellular response to infection." (PMID 40725231, 2025). "The expression of ATF2 and IRF5 transcription factors was downregulated by VSV-infection." (PMID 34578166, 2021). "HOMER analysis detected the enrichment of motifs in the promoters of differentially expressed genes for NF-κB and the MAPK-activated transcription factor SRF, indicating that these pathways are likely upstream of AP-1/ATF-2/NFAT-mediated gene expression, as detected by RNAseq at 6 h post-infection." (PMID 29868516, 2018). "Of these three transcription factors, we have only obtained a DNA binding site for cTf4, which is, like the DNA binding sites of aTf2, aTf5 and aTf7, not enriched among genes up- or down-regulated during infection." (PMID 27855160, 2016). "infection for robust intestinal regeneration, suggesting that additional mechanisms may increase Duox activity and that its increased activity upon infection is not solely through its transcriptional upregulation via Atf2." (PMID 31554796, 2019). "Together these data suggest that p38a + b signaling promotes intestinal regeneration upon infection via Upd3/JAK-STAT signaling, and not through Atf2-mediated Duox expression." (PMID 31554796, 2019). "We have previously shown that NSs inhibits IFN-β expression immediately after infection with the virulent RVFV strain ZH548 (ZH), without inhibiting IFN-β-specific transcription factors such as IRF3, NF-κB and ATF2 that are normally activated and translocated to the nucleus in RVFV-infected cells." (PMID 18225953, 2008).
neurodegenerative disease (6 papers, 2015 to 2024). A disorder of the central nervous system characterized by gradual and progressive loss of neural tissue and neurologic function. "The most recent research field, treating neurodegenerative diseases with microRNAs, can be used to modulate any aberrant expression of ATF2 target genes and subsequent abnormality leading to neuronal degradation or to provide sufficient neuronal protection." (PMID 32993798, 2020). "So, exploiting this information, it can be analyzed if ATF2 and hsa-miR-933 can play a neuroprotective role in neurodegenerative diseases by regulating their common target gene BDNF." (PMID 32993798, 2020). "The present findings not only connect cytoplasmic ATF2 with ischemic neurodegeneration, but also suggest that PKCε is a master switch regulating neuronal survival and degeneration in various types of neurodegenerative diseases." (PMID 30497386, 2018). "So, exploiting this information, it can be analyzed whether ATF2 and hsa-miR-933 can play a neuroprotective role in neurodegenerative diseases by regulating their common target gene BDNF." (PMID 32993798, 2020). "Moreover, we showed that hsa-miR-933 can regulate a target of ATF2, brain-derived neurotrophic factor (BDNF), to modulate the optimal expression of ATF2 in neuron cells to render neuroprotection for the inhibition of neurodegenerative diseases." (PMID 32993798, 2020). "Accordingly, ATF-2 may potentially function as a critical molecular target for drug therapies in neurodegenerative diseases." (PMID 30526621, 2018).
cardiovascular disorder (1 paper, 2021). A disease involving the cardiovascular system. "To date, very few studies have explored the role of ATF2 in the pathogenesis of cardiovascular disorders." (PMID 34272480, 2021).
heart diseases (1 paper, 2017). "ATF2, the seventh most significant gene, was reported to be possibly involved in Alzheimer’s and heart diseases." (PMID 29322921, 2017).
metabolic disorders (1 paper, 2024). "These pathways activate multiple signals including EIK-1, c-Jun, ATF-2, c-Fos, Myc, and STAT1 which involve in cell migration and invasion, cellular proliferation, cell survival, and metabolic disorders." (PMID 39149564, 2024).
psychiatric disorder (1 paper, 2018). A disorder characterized by behavioral and/or psychological abnormalities, often accompanied by physical symptoms. "In this way, the linking of p38 MAPKs and CREB/ATF2-induced COX-2 upregulation by βCaMKII might be a key factor in the pathogenesis of this psychiatric disorder." (PMID 30526621, 2018).
respiratory disorder (1 paper, 2011). "Can individual or combinations of these defects explain the early postnatal respiratory disorder and death of ATF2 mutant mice?" (PMID 21533046, 2011).
ATF2 also shares sentences with these, for which no sentence is quoted: Huntington disease (5 papers); benign prostatic hyperplasia (2); colitis (2); epilepsy (2); gastric adenocarcinoma (2); metastatic melanoma (2); pancreatic adenocarcinoma (2); prostate tumor (2); acne (1); acute kidney injury (1); Alzheimer disease (1); atopic dermatitis (1); autoimmune disease (1); Azoospermia (1); brain hemorrhage (1); breast tumour (1); chordoma (1); cocaine addiction (1); cognitive disorder (1); colorectal adenoma (1); Crohn disease (1); cryptorchidism (1); diffuse large B-cell lymphoma (1); Dyskinesia (1); fatty liver disease (1); gastritis (1); hematological cancer (1); hypercalcaemia (1); Hyperinsulinemia (1); inflammatory bowel disease (1).
A further 21 diseases each share a sentence with ATF2 in 1 paper.